CDK9 (cyclin dependent kinase 9)
Diseases named in the same sentence as CDK9 in open-access papers (continued):
Sharing a sentence is not in itself a finding about the gene and the disease.
tumor (continued). "It is conceivable that acetyl-bufalin can be further explored as a unique CDK9 inhibitor for anti-tumour therapy." (PMID 33122847, 2021). "In this context, inhibitors targeting the transcription-associated CDKs (including CDK7, CDK8, CDK9, CDK12, and CDK13) have gained attention as attractive candidates to suppress tumor-specific signaling cascades." (PMID 34359807, 2021). "Further, CDK9 has been suggested to play a role in maintaining gene silencing at heterochromatin loci, thus suppressing the expression of tumor suppressive genes." (PMID 34359807, 2021). "We envisage that inhibitors targeting CDK9 would provide significant anti-tumor activity, as a single agent or in combination with other established therapies, in NSCLC." (PMID 34359807, 2021). "We were intrigued by the finding that CDK9 activity is required for Yki-driven tumor formation, even when the upstream and downstream pausing complex factors have been removed." (PMID 32737120, 2020). "Seliciclib, a first generation aminopurine inhibitor of CDK2, CDK7 and CDK9, has shown anti-proliferative activity in tumor cell lines and xenografts." (PMID 32645016, 2020). "CR8 was shown to target similar Cdks as Roscovitine including Cdk1, Cdk2, Cdk5, Cdk7 and Cdk9, but with much stronger efficacy and a predicted improved anti-tumor potential." (PMID 32380742, 2020). "A systematic study of enzymatic and cellular assays led to the identification of compound X22 with a nanomolar potency against CDK4 and CDK9 and potent antiproliferative activities against a panel of tumour cell lines." (PMID 31899991, 2020). "Several compounds inhibited CDK4 and CDK9 at low nanomolar levels and exhibited good antiproliferative activities in a panel of tumour cells." (PMID 31899991, 2020). "Roniciclib binds to and inhibits the activity of CDK1/Cyclin B, CDK2/Cyclin E, CDK4/Cyclin D1, CDK6/Cyclin D3, and CDK9/Cyclin T1, which are serine/threonine kinases playing key roles in the regulation of tumor cell proliferation and survival." (PMID 32737364, 2020). "The median percent tumor fibrosis for control, CDK9 inhibitor-, radiation-, and combination-treated cells were 15, 10, 20, and 30, respectively." (PMID 31384397, 2019). "The ability of continuous single-agent BAY1143572 to suppress tumor regrowth after radiation indicates that this CDK9 inhibitor can maintain the anti-tumorigenic effects of radiation." (PMID 31384397, 2019). "Western blot analysis of the tumours collected from xenografted mice treated with CDKI‐73 confirmed its inhibition of CDK9 in vivo." (PMID 31398271, 2019). "In vivo synergy between the CDK9 inhibitor and radiation was assessed in multiple xenograft models including a patient’s tumor derived xenograft (PDX)." (PMID 31384397, 2019). "That the combination had higher efficacy is also supported by the high degree of tumor necrosis and stromal fibrosis in the xenografts after pretreatment with CDK9 inhibitor followed by radiation." (PMID 31384397, 2019). "The additive radiation enhancing effect of CDK9 inhibitor was found to be greater at higher radiation doses, indicating a low likelihood of plateauing effects of radiation-mediated tumor cell damage." (PMID 31384397, 2019). "We further evaluated its potency in inhibiting anchorage-independent growth of tumor spheroids with respect to commonly used chemotherapeutic drugs and CDK9 inhibitors." (PMID 31527550, 2019). "Treatment with 17.5 mg/kg the CDK9 inhibitor for 20 days plus 5 Gy of radiation once on day 4 reduced PDX tumor volumes by 67% compared with radiation alone (p = 0.016) and by 48% compared with the CDK9 inhibitor alone (p = 0.062)." (PMID 31384397, 2019). "The treatment resulted in the reduction of known CDK9 targets, i.e. Bcl‐2 and Mcl‐1 in tumour tissues." (PMID 31398271, 2019).
tumor (continued). "To determine if metformin potentiates the anti-tumor activity of novel targeted agents, we tested the combination of metformin with either a bcl-2 inhibitor (Venetoclax) or CDK9 inhibitor (BAY-1143572) or PI3K inhibitor (Idelalisib)." (PMID 29765528, 2018). "A total of 84 patients were analyzed for tumor expression levels of CDK9 using the TMA staining protocol." (PMID 30405916, 2018). "It is evident that miR‐206 functions as a tumor suppressor through blocking CDK9‐related pathway to induce apoptosis and inhibit HCC cell proliferation." (PMID 28940993, 2017). "Our data on CDK9 identifies that CDK9 inhibition is an important mechanism the anti-tumor effect of dinaciclib and establishes CDK9 as a potential therapeutic target for MYC driven TNBC." (PMID 27486754, 2016). "In the FNA-PDX tumor, we identified molecular lesions that predicted response to targeted therapies (CDK9 inhibition) identified through high-throughput screens." (PMID 26934555, 2016). "CLL expressed significantly lower levels of CDK9 compared to normal donors, suggesting a potential therapeutic index between these tumor cells and normal cells if targeting this is the predominate mechanism of action." (PMID 25596730, 2015). "Here we provide proof-of-concept that cdk9 plays a key role in tumor cell survival as selective cdk9 inhibition." (PMID 24495868, 2014). "Flavopiridol has been shown to inhibit multiple CDKs and other kinases, but the primary mechanism responsible for its observed anti-tumor activity in CLL appeared to be the CDK9-mediated down-regulation of transcription of anti-apoptotic proteins." (PMID 25277198, 2014). "Over 80% (30/35) of panCK+ tumor cells expressed CREPT while 57% expressed CDK9." (PMID 40860160, 2025). "However, CDK9 expression showed only a modest increase in tumor tissues compared to adjacent non-tumor tissues." (PMID 40860160, 2025). "The tumor stage was higher in patients with higher CDK9 expression, suggesting that a higher CDK9 could predict the course of OC." (PMID 40361480, 2025). "CDK9 expression is high in tumor tissue, particularly in well-differentiated malignancies." (PMID 40361480, 2025). "Our findings are in accord with recent studies that targeting of CDK9 has reduced the downstream phosphorylation of RNA Pol II at Ser2 and decreased nascent transcripts synthesis, showing promising in vitro and in vivo anti-tumor activity in carcinogenesis." (PMID 41360777, 2025). "Disruptions in this balance, such as through mutations in INTS6 or INTS11, lead to aberrant transcriptional elongation, resistance to CDK9 inhibition, and amplified oncogenic transcriptional responses, linking the INTS complex to both transcriptional regulation and tumor susceptibility." (PMID 40966122, 2025). "AZD4573 (AstraZeneca) is another highly potent CDK9 inhibitor with >25-fold selectivity for CDK9 over other CDKs; it has demonstrated broad anti-tumour activity in preclinical studies and in a clinical trial of relapsed haematological malignancies (NCT03263637)." (PMID 40163908, 2025). "Intriguingly, our multiplex IF analysis revealed CREPT and CDK9 expression not only in tumor cells but also in other cells within the tumor microenvironment, suggesting that CREPT may also modulate the tumor microenvironment." (PMID 40860160, 2025). "Furthermore, we report on a newly developed, highly specific CDK9 inhibitor, VC-1, with tumour-killing activity in SCLC." (PMID 38769311, 2024). "We therefore hypothesized that targeting CDK9 may turn off MYC-driven tumor survival and drug resistance." (PMID 38886769, 2024). "Moreover, simultaneous blockade of the complement system and CDK9 significantly impeded immune evasion and retarded tumor growth in KRAS‐mutant xenografts." (PMID 39254172, 2024). "A multiplicity of tumour-intrinsic factors may influence relative response to CDK9 inhibition in TNBC." (PMID 38001268, 2024).
tumor (continued). "Moreover, we found pronounced CDK9 expression in tumor samples of patients with HB, with high expression being associated with clinical risk factors such as increased patients’ age and immature histology, but most importantly, poor prognosis." (PMID 37729391, 2024). "Given the intricate crosstalk between CDK9 and other signaling pathways, combination therapy may offer a potential strategy for mitigating drug toxicity and overcoming tumor resistance." (PMID 39254172, 2024). "Further studies combining CDK9 inhibition with immune checkpoint blockade in SCLC might show improved anti-tumour immunity, thus improving the outcome of immunotherapies in SCLC patients." (PMID 38769311, 2024). "Besides, YY1 interacts with cyclin-dependent kinase 9 (CDK9) to regulate transcriptional elongation in GSCs, thereby inducing interferon response and reconnecting the tumor microenvironment of GBM." (PMID 38561775, 2024). "HSPs, therefore, may serve as functional associated activators with the CDK7/CDK9–Rpb1 complex, akin to TLR4 activation in tumor-induced muscle wasting." (PMID 38858714, 2024). "Thus, CDK9 inhibition not only represses oncogenes, but also reactivates silenced tumor suppressor genes and induces tumor cell immune responses, making it a promising epigenetic therapy." (PMID 38172923, 2024). "Continued efforts to explore the molecular mechanisms underlying the inhibitory effects, and to identify suitable tumor genotypes and combination treatment strategies, are crucial to demonstrate the efficacy of selective CDK9 inhibitors and degraders in tumor therapy." (PMID 37272701, 2023). "CDK9 inhibition by flavopiridol can remarkably attenuate tumor growth in vitro and in vivo." (PMID 35088192, 2023). "We further tested the anti-tumor efficacy of combined CDK9/PIM1 inhibition in vivo." (PMID 36998071, 2023). "Furthermore, when subdivided by tumor size, we found a correlation between high CDK9 expression and increased overall survival of CRC patients with T3/T4 tumors (p = 0.044)." (PMID 36979907, 2023). "Additionally, the CDK9 inhibitors delayed tumor growth, increased survival and demonstrated therapeutic benefits in orthotopic xenograft models of DMG." (PMID 36154607, 2023). "A number of studies have now indicated CDK7 and CDK9 play a role in maintaining genome stability, and inhibition of their activity may sensitise tumours to immune checkpoint inhibitors." (PMID 35568739, 2022). "Options to specifically degrade CDK9 in the tumor should be pursued." (PMID 35628286, 2022). "CDK9 detection was significantly increased (p = 0.014) in tumors with high caspase-8 expression but did not display a correlation with age, T-stage, N- and M-stage, tumor grading and FIGO category." (PMID 36428594, 2022). "A CDK9 inhibitor SNS-032 has been reported to have good effects in anti-tumor." (PMID 36313366, 2022). "Consequently, CDK9 inhibition induces the infiltration of T cells and activates dendritic cells into the tumor environment, which is further potentiated by PD-L1 inhibition." (PMID 36139513, 2022).
tumor (continued). "Targeting CDK9 may be a promising approach due to its ability to modulate various cellular mechanisms to initiate an anti-tumor response, as discussed in this review." (PMID 34207158, 2021). "The inhibition of anchorage independent growth is of specific interest as this may suggest that CDK9 inhibitors will be able to interfere with steps involved in tumor dissemination and metastasis." (PMID 34359807, 2021). "Acetyl-bufalin can exert anti-tumour effect by inhibiting the CDK9/STAT3 signalling pathway." (PMID 33122847, 2021). "CDK9 inhibition may serve then as a strategy to upregulate IFN-γ-stimulated genes that promote anti-tumor effects while mitigating immunosuppressive effects elicited by IDO1." (PMID 34207158, 2021). "Analysis of cells treated with AZD4573 showed that the levels of Sox2 and Sox9 are reduced, implying that inhibiting CDK9 might prevent their tumor promoting functions." (PMID 34359807, 2021). "We also found that CDK9 outperforms Ki-67 as a predictor of tumor recurrence in EOC." (PMID 34011401, 2021). "Furthermore, by Co-IP experiments, we demonstrated a direct interaction of BRD4 with phosphorylated CDK9 in EwS, as previously shown in other tumor entities." (PMID 32012890, 2020). "CDKI-73 has been described as a new promising CDK9 inhibitor for several tumor entities." (PMID 32012890, 2020). "Pin1 also catalyzes the isomerization of Pro205 of Brd4 and induces its conformational change through a cis-trans isomerization, which leads to enhanced CDK9 binding to Brd4 and enhanced recruitment of CDK9 to a subset of promoters of Brd4-mediated tumor-promoting genes, including c-MET and MMP9." (PMID 32266261, 2020). "In agreement, modulation of CDK9 has been recently shown as a promising strategy to hamper the transcriptional machinery in tumors types that are strictly dependent on aberrant transcription from tumor-driver oncogenes." (PMID 32903585, 2020). "Together these observations suggest that CDK9 inhibition might be effective in high CDK9-expressing TNBCs as it exhibits antineoplastic effects in tumor cells and additionally disrupts tumor-initiating CSLCs." (PMID 30647871, 2018). "Together, our data suggest that CDK9 inhibitors may have single-agent anti-tumour activity against a subset of SCLC that either carry c-MYC amplification or are MCL-1-addicted." (PMID 28714472, 2017). "Notably, CDK9 inhibitor treatment of mice inoculated with bortezomib-sensitive or -resistant MM cells yielded approximately equivalent reductions in tumor burden, clearing of marrow, and restoration of marrow architecture." (PMID 28938651, 2017). "Collectively, these results showed that the inhibition of CDK2 and CDK9 activity by dinaciclib could block NB growth and induce tumor cell death in vivo." (PMID 27378523, 2016). "Together, these results showed that the inhibition of CDK2 and CDK9 activity by dinaciclib could block NB tumor development and induce tumor cell death in TH-MYCN transgenic mouse model." (PMID 27378523, 2016). "In explant cells derived from these PDX tumor models with a KRAS G12R mutation, treatment with inhibitors of CDKs (including CDK9) reduced phosphorylation of a marker of CDK9 activity (phospho-RNAPII CTD Ser2/5) and reduced viability/growth of explant cells derived from PDAC PDX models." (PMID 26934555, 2016). "As a consequence, the combination of TRAIL and CDK9 inhibition is exquisitely powerful in killing tumor cells with a cFlip-imposed block to initiator caspase activation at the DISC and an Mcl-1-imposed block to activation of the mitochondrial apoptosis pathway." (PMID 24362439, 2014).
tumor (continued). "Moreover, we propose that this approach may have fewer on-target off-tumor effects compared to direct CDK9 inhibition in LUAD, due to the specific elevation of CREPT expression in LUAD tumor tissues." (PMID 40860160, 2025). "Given that CREPT exhibited strikingly higher expression in tumor tissues and its inhibition showed comparable inhibitory effects to CDK9 inhibitors on tumor growth, we hypothesize that targeting CREPT may provide an alternative and potentially more specific strategy for LUAD treatment." (PMID 40860160, 2025). "Notably, the tumor-suppressive effect of CREPT depletion was comparable to that of CDK9 inhibition, suggesting that targeting CREPT could effectively recapitulate the tumor-suppressive effects of CDK9 inhibition." (PMID 40860160, 2025). "Hence, our results suggest that CDK9 inhibition by either dinaciclib or VC-1 treatment could impair SCLC tumour growth and that both drugs, especially VC-1, are well tolerated in vivo." (PMID 38769311, 2024). "The BCMP model was the most sensitive to CDK9 inhibition, likely due to the exceptionally high rate of proliferation driven by ectopic overexpression of four oncogenes, supporting the importance of CDK9 in sustaining the high rate of transcription characteristic of rapidly proliferating tumours." (PMID 38001268, 2024). "Additionally, CDK9 inhibitors are widely used in clinical tumor treatment." (PMID 36082129, 2022). "The anti-apoptotic proteins Mcl1 and XIAP are known targets of CDK9, and suggests that CDK9 inhibition brings about its effects by suppressing anti-apoptotic or pro-survival signaling, while simultaneously activating pro-apoptotic and tumor-suppressive pathways." (PMID 34359807, 2021). "Thus, miR-206 downregulates CDK9 expression and inhibits tumor growth." (PMID 31578445, 2019). "In addition, CDK9 also contributed to altered apoptosis in non-tumor cells." (PMID 31758083, 2019). "Thus, we employed the Matrigel-assisted 3D-on-top culture method to investigate whether anti-tumor effects of atuveciclib observed in high-CDK9 TNBC cell lines grown in 2-dimensional (2D) culture could be reproduced in 3D." (PMID 30647871, 2018). "MCL1 levels varied between patient tumour tissues and MCL1 intensity correlated with CDK9 intensity." (PMID 41505030, 2026). "To assess CDK9 as a potential target in TNBC, we evaluated CDK9 expression levels on previously established tissue microarrays (TMA) of 384 TNBC patient tumours." (PMID 41505030, 2026). "In metastatic TNBC models, complex 8 reduced the coprecipitation between CCNT1 and CDK9 and decreasedmRNA levels of c-MYC and Mcl-1 in tumor tissues, which suggested thatcomplex 8 disrupted the CDK9–CCNT1 PPI in vivo." (PMID 41152016, 2025). "Quantitative analysis (n = 10) revealed that pan-cytokeratin-positive (panCK+) tumor cells accounted for approximately 35% of total cells, with CREPT-positive (CREPT+) and CDK9-positive (CDK9+) cells comprising 77% and 40 %, respectively." (PMID 40860160, 2025). "By performing principal component analysis on the AUC values, we discovered HSP90 inhibitors as one of the most effective and tumor-suppressing drug categories, grouping them alongside HDAC and CDK9 inhibitors." (PMID 40282517, 2025). "In dendritic cells, JAK1/STAT3 signaling represses IL-12 production by inhibiting the recruitment of cyclin-dependent kinase 9/positive transcription elongation factor b (CDK9/P-TEFb) to the IL-12p35 promoter, thereby impairing anti-tumor immune responses." (PMID 40867898, 2025). "On the other hand, we found that CDK9, CREPT, and panCK triple positive cells constituted about 19% in tumor tissues while over 90% of CDK9+panCK+ double positive cells expressed CREPT." (PMID 40860160, 2025).